CSF1R (colony stimulating factor 1 receptor)
Diseases named in the same sentence as CSF1R in open-access papers (continued):
Sharing a sentence is not in itself a finding about the gene and the disease.
tumor (continued). "Increasing evidence supports that CSF1R affects tumor-associated macrophages (TAMs) to promote tumor progression." (PMID 32801364, 2020). "Colony-stimulating factor 1 receptor (CSF-1R) has been found to be restrictively expressed by tumor associated macrophages (TAMs) and monocytes which more prefer to locate at the boundary of HCC." (PMID 32760707, 2020). "Some researchers found that colony-stimulating factor 1 receptor (CSF-1R) expression and tumor associated macrophage (TAM) density (CSF-1 receptor, CSF-1R or CD68) in the adjacent liver tissues are associated with patient survival after resection of HCC." (PMID 32760707, 2020). "CSF-1R is involved in several human diseases, its constitutive inactivating mutation induces a leuko-encephalopathy while its stimulation supports tumor progression and chronic inflammatory diseases." (PMID 31028249, 2019). "Macrophage colony-stimulating factor (M-CSF), on the other hand, is a secreted cytokine that causes macrophages to differentiate into tumor-associated macrophages (TAM) by binding to the colony stimulating factor 1 receptor (CSF1R)." (PMID 31277684, 2019). "The administration of the CSF1R inhibitor (AZD7507) caused a reduction in tumor burden and was associated with improved overall survival in murine models." (PMID 30987642, 2019). "The CSF-1/CSF-1R axis plays a key role in macrophage differentiation, proliferation and survival, especially for M2-like tumor-associated macrophages (TAMs)." (PMID 31438996, 2019). "CSF1R inhibition is associated with reduced immune suppression, enhanced tumor regression and activation of antitumor immune cells as a consequence of a reduced percentage of TAMs to support antigen presentation and T cell activation within the TME." (PMID 30987642, 2019). "Outside of MDSCs, RENCA tumors uniquely express high levels of CSF1R, which is found in numerous cell types (monocytes, DCs, neutrophils, eosinophils) including immunosuppressive tumor associated macrophages (TAMs)." (PMID 30388137, 2018). "CSF1R is a receptor tyrosine kinase that mediates tumorigenesis in tumor-immune microenvironments and is expressed on tumor-associated macrophages (TAMs); the high expression levels of CSF1R correlate with poor survival in patients with various malignancies." (PMID 30065206, 2018). "Calculation of the ESTIMATE score, to infer tumor purity, and of the stromal score revealed that CSF-1 and CSF-1R are strongly linked to the stromal compartment in all subtypes." (PMID 29796177, 2018). "CSF1R-expressing tumor-associated macrophages (TAMs) induce a tumor-promoting microenvironment by regulating immunity." (PMID 30065206, 2018). "In the tumor microenvironment, colony‐stimulating factor 1 receptor (CSF1R) is expressed on tumor associated macrophages and MDSC which can play critical roles suppressing the cytotoxic immune response." (PMID 30003190, 2018). "CSF1R is expressed on tumor-associated macrophages (TAMs), and mediates important pro-tumorigenic functions." (PMID 29323162, 2018). "The TKI pexidartinib (PLX3397) blocks the CSF1/CSF1R axis, which inhibits tumor-associated macrophage infiltration along with autocrine and paracrine signaling of CSF1 to inhibit tumor cell growth." (PMID 30450193, 2018). "Given the pro-angiogenic properties of tumor-associated macrophages (TAMs) and the dominant role of CSF1R in macrophage function, we added CSF1R inhibitors following emergence of adaptive resistance to anti-VEGF antibody." (PMID 29228548, 2017). "Accumulating evidence suggests that CSF-1 and its receptor, CSF-1R, are implicated in tumor development and progression." (PMID 28170411, 2017). "Preclinical models have linked the inhibition of CSF1/CSF1R signaling to the reprogramming of the monocytoid population, shifting the population from tumor promoting monocytes (MDSCs) to that of tumor suppressive, antigen presenting macrophages." (PMID 28492495, 2017).
tumor (continued). "A relatively new therapeutic target in CLL is colony-stimulating factor 1R (CSF1R), expressed on tumor-associated macrophages (TAMs), and macrophage killing by CSF1R blockade induces CLL cell death, primarily through the tumor necrosis factor pathway." (PMID 29152232, 2017). "Macrophages flocked to the tumour, the so-called tumour-associated macrophages (TAMs), are generally recruited by the activation of CSF1R by CSF-1 or IL-34, as well as by the chemokine CCL2." (PMID 28404796, 2017). "The aim is to inhibit the tumor-induced immune suppression with nivolumab, and to block with cabiralizumab the recruitment of CSF1R-dependent tumor-associated macrophages (TAMs)." (PMID 29312320, 2017). "The CSF1R expression has been reported on MDSCs, tumor-associated macrophages (TAMs), and dendritic cells and regulates survival, differentiation, and proliferation of monocytes and macrophages and has a critical role in angiogenesis and tumor progression." (PMID 29258180, 2017). "FGFR and CSF1R also appear to induce tumor-associated macrophage proliferation and differentiation, thereby promoting tumor immune evasion." (PMID 28159938, 2017). "On the other hand, Nur77-deficient macrophages had low tumor-infiltrating migratory ability due to downregulation of CSF-1R expression, a novel target gene of Nur77." (PMID 28170411, 2017). "Dasatinib, an Src gene inhibitor, makes it difficult for melanoma tumour cells to survive as CSF-1R, a regulator or the macrophages associated with tumours, inhibits apoptosis, migration, and invasion in the breast cells of canines." (PMID 26913068, 2016). "It has been also reported that the selective pharmacologic inhibition of CSF1R signaling resulted in the decreased tumor angiogenesis associated with reduced recruitment of MDSCs into the tumor site." (PMID 27827871, 2016). "In the murine model of this study, we monitored simultaneously 59 immune cell parameters and demonstrated that splenic myeloid cells expressing PD-L1 and CSF-1R at high levels were associated with larger tumor burdens." (PMID 28123870, 2016). "CSF1R antagonist can suppress the infiltration of MDSCs and tumor-associated macrophages (TAMs) to the site of tumor." (PMID 26078490, 2015). "Nevertheless, CSF-1R is a therapeutic target in oncology, either to inhibit a paracrine loop that promotes tumor growth or to re-educate tumor associated macrophages (TAMs) within tumor microenvironment." (PMID 24828813, 2014). "CSF-1/CSF-1R signaling is important for tissue homeostasis, repair, and inflammation and acts as a chemoattractant for the recruitment, production, and survival of tumor-associated macrophages (TAMs) in the tumor microenvironment." (PMID 40646332, 2025). "Taken together, these results imply that the elevated expression of Csf1r caused by Mir34a-deficiency may play a major role in tumor progression via TME—tumor cell interactions in the mouse model analyzed here." (PMID 39425000, 2025). "Approaches that target tumor-associated macrophages, such as CSF1R inhibition, CD40 agonists, or TLR/STING agonists, may promote M1 polarization and strengthen innate antitumor activity." (PMID 41374320, 2025). "Within a detrimental TME, infiltrating MAIT cells display an exhausted phenotype, largely driven by tumor-associated macrophages (TAMs), which induce dysfunction through increased expression of CSF1R+ (colony stimulating factor 1 receptor), PD-L1+ (programmed cell death ligand 1), and CD69+." (PMID 40746558, 2025). "These include combining immune checkpoint blockade (ICB) with chemotherapy, anti–TGF-β agents, CSF1R inhibitors that target tumor-associated macrophages (TAMs), or intravesical immunomodulatory agents designed to remodel the tumor immune microenvironment and enhance antitumor immunity." (PMID 41256858, 2025). "Furthermore, in anti-tumor therapy involving CSF1R blockade, tumor-associated fibroblasts recruit PMN-MDSCs, thereby diminishing therapeutic efficacy." (PMID 41029721, 2025).
tumor (continued). "Moreover, CSF1R inhibition has been associated with fibrosis within the CNS, which can create a protective niche for tumor cells." (PMID 40800581, 2025). "Additionally, CSF1R plays a significant role in the chemotaxis and accumulation of tumor-associated macrophages." (PMID 39865310, 2025). "They found that the CSF-1/CSF-1R signaling pathway induced hematopoietic progenitor cells and stem cells derived from bone marrow within the tumor differentiating into M2 tumor-associated macrophages, which contributed to tumor survival and regeneration after radiotherapy." (PMID 40007537, 2025). "Moreover, CSF1R blockade can effectively deplete MDSCs and reprogram tumor-associated macrophages toward a tumor-suppressive (M1-like) phenotype, thereby enhancing antitumor immunity." (PMID 40808954, 2025). "Therefore, Csf1r is a required mediator of the effects of Mir34a inactivation in tumor-associated myeloid cells." (PMID 39425000, 2025). "CSF1R inhibitors have attracted great interest as promising therapeutic agents, particularly in cancer, mostly because of their ability to modulate tumor‐associated macrophages, which typically present an immunosuppressive phenotype that aids tumor progression." (PMID 39448548, 2025). "This has led to the consideration that anti-CSF-1R therapies could be beneficial not only in reducing the presence of M2-like tumor-associated macrophages (TAMs) but also in targeting cancer cells themselves." (PMID 39457693, 2024). "The CSF1/CSF1R signaling pathway plays an important role in macrophage exhaustion, and its activation induces macrophage exhaustion, causing them to lose their anti-tumor function and instead support tumor growth and immune escape." (PMID 39416792, 2024). "As previously reported, the CSF-1R is a typical myeloid receptor, but under inflammatory conditions it can undergo a different type of regulation, as happens in cancer cells and cells associated with the tumor microenvironment (TME)." (PMID 39457693, 2024). "Additionally, CSF-1R expression was found in the cancer cell membrane of different tumor types, where it is associated with the main cancer hallmarks including increased proliferation, migration and drug resistance." (PMID 38254773, 2024). "Additionally, colony-stimulating factor 1 receptor (CSF1R) and granulocyte macrophage-colony stimulating factor (GM-CSF) can regulate the activity of tumor-associated macrophages (TAM)." (PMID 39835140, 2024). "In contrast, interventions aiming at the depletion of these tumour-associated myeloid cells through the inhibition of colony-stimulating factor-1 receptor (CSF-1R) whose downstream signalling is required for their survival, have been reported to reduce, at least transiently, GB expansion." (PMID 39019900, 2024). "Consequently, the presence of CSF‐1R‐expressing myeloid cells within the tumor is associated with decreased survival rates in many malignancies." (PMID 38077251, 2023). "Additionally, to understand the role of MYC overexpression in OS regulating Csf1r expression in tumor-associated macrophages, we analyzed their expression at transcription and protein levels." (PMID 37279073, 2023). "Furthermore, CSF-1R blockade only caused a modest delay in tumor growth, thus yielding only limited therapeutic success." (PMID 36902456, 2023). "CSF-1R inhibition causes a substantial decrease in tumor-associated macrophages." (PMID 36798830, 2023). "The presence of macrophages expressing CSF1R within tumors is linked to low survival rates in a variety of cancers, indicating that efforts to target these CSF1R+ tumor-associated macrophages may aid in tumor clearance." (PMID 37266435, 2023). "The inhibition of the colony-stimulating factor 1 receptor (CSF-1R) implicated in the regulation of tumor-associated macrophages (TAM) whose role in carcinogenesis, resulting from the inhibition of tumor infiltration by leukocytes, confers to Regorafenib an immuno-modulating role." (PMID 37909027, 2023).
tumor (continued). "Some preclinical models showed that CSF-1R inhibition causes reduced TAMs and tumor growth." (PMID 36902456, 2023). "The inhibition of tumor growth mediated by A20 deficiency could be restored by the deletion of macrophages with CSF1R antibody in mice." (PMID 37607946, 2023). "The association of CSF-1R with these tumor immune checkpoint molecules indicates that CSF-1R may also serve as a valuable biomarker for predicting prognosis and an immunotherapeutic strategy against COAD." (PMID 35444953, 2022). "(b) CSF-1R: CSF-1R is a tyrosine kinase receptor that, when bound with its ligand CSF-1, not only promotes the migration of MDSCs but also can differentiate and expand myeloid cells into MDSCs and tumor-associated macrophages (TAMs)." (PMID 35628647, 2022). "Among these immune-associated ligands and receptors, CTLA4, CCR5 and CSF1R could contribute to tumor immune suppression, while TNFRSF1B and type II IFNR are associated with stimulation in neutrophils." (PMID 36443332, 2022). "Therefore, the up-regulation of Csf1r presumably mediated the effects of Mir34a loss on the tumor microenvironment." (PMID 36147476, 2022). "In addition to VEGFR1, surufatinib also targets colony stimulating factor 1 receptor (CSF1R) that mediates the polarization of tumor-associated macrophages (TAM, M2 phenotype)." (PMID 36344509, 2022). "Extensive overexpression of CSF-1 can be observed at the invasive edge of the various tumor, and it is involved in the polarization of M2 macrophages by interacting with its ligand CSF-1R; Its overexpression is also associated with a significant increase in metastasis." (PMID 36131942, 2022). "In tumors, tumor-associated macrophages are also dependent on CSF-1R signaling for their survival." (PMID 35806328, 2022). "First, CSF-1R regulates tumor-associated macrophages (TAM) to promote tumor progression." (PMID 36555673, 2022). "In addition, FGFR and CSF1R stimulate tumour-associated macrophage proliferation and differentiation, thus promoting tumour immune evasion." (PMID 35408830, 2022). "It was reported that CSF1/CSF1R blockade-based anti-tumor therapy could result in loss of macrophages in the tumor either by mitigating recruitment, TAMs survival and/or differentiation from monocytes." (PMID 34248982, 2021). "Moreover, the CSF1/CSF1R pathway is a dominant regulator of macrophage differentiation and function, with studies showing that CSF1R inhibition can deplete tumor associated macrophages and improve T cell responses." (PMID 33796453, 2021). "Therefore, it is important to explore the CSF-1 and CSF-1R signaling pathways related to tumor-associated macrophages (TAM) and their specific mechanisms in the comprehensive prevention and treatment of gastrointestinal malignancies." (PMID 34729112, 2021). "Moreover, microenvironmental alterations by CSF1R blockade rendered tumor cells susceptible to receptor tyrosine kinase inhibitors dovitinib and vatalinib in preclinical studies." (PMID 34063518, 2021). "Despite the known relationship between tumor-associated macrophages and poor clinical outcome, the detailed mechanisms mediating different outcome between patients with CSF1R c.1085 genotypes A_A and A_G remain unclear." (PMID 34830445, 2021). "Interestingly, these results were perfectly in vivo transferable, where CSF-1R inhibition alone was sufficient to cause a significant reduction (40%) of tumor growth." (PMID 33731849, 2021). "In addition, regorafenib reduced tumor-associated macrophages in tumor models by inhibiting other targets, including colony-stimulating factor 1 receptor." (PMID 34622226, 2021).
tumor (continued). "Colony stimulating factor-1 (CSF-1), a polypeptide chain cytokine, and its receptor CSF-1R are reported to play important roles in regulating tumor-associated macrophages in tumor microenvironment and participating in the occurrence and development in diversities of cancers." (PMID 34729112, 2021). "CSF1/CSF1R signaling mediates tumor-associated macrophages recruitment and M2 polarization." (PMID 34067348, 2021). "We speculated that this tumor shrinkage was caused by inhibition of CSF-1R in macrophages with TAS-115." (PMID 31820255, 2020). "Furthermore, CSF1R hypomethylation in ANTs was associated with a larger number of tumors (P=0.0332), larger tumor size (P=0.0494) and higher tumor grade (P=0.0244)." (PMID 32724427, 2020). "Importantly, a strong correlation of CSF-1 expression with CSF-1R-positive tumor-associated macrophage infiltration has also been detected in human carcinomas." (PMID 32637413, 2020). "Moreover, CSF-1 and CSF-1R are also expressed in tumor-associated macrophages (TAMs), promoting tumor progression and metastasis in several cancers." (PMID 31565097, 2019). "Further Targeting C-C motif chemokine receptor 2 (CCR2) or colony stimulating factor 1 receptor (CSF1R) rallies chemotherapeutic efficacy inhibits metastasis and increases anti-tumor T-cell responses by causing a reduction in the number of tumor-initiating cells (TICs) in PDAC." (PMID 30925924, 2019). "For example, blocking the CSF-1/CSF-1R axis or targeting the pattern recognition receptor MARCO causes a phenotypic shift from M2-like macrophages to M1-like macrophages resulting in increased tumor immunogenicity." (PMID 30619850, 2018). "In this study, we demonstrate that the level of expression of CSF-1R within the lymphoid aggregates induced by GVAX affects the tumor immune microenvironment; high CSF-1R expression is associated with an immunosuppressive environment in patients who received GVAX." (PMID 30424804, 2018). "Additionally, anti-CSF-1R antibody was also tested to target tumor-associated macrophages and revert their inhibitory effect on the immune response." (PMID 29755681, 2018). "Consistent with the role of CSF-1-dependent, TAM-activated tumor invasion, high CSF-1 levels are also associated with poor prognoses in many cancers, leading to the testing of a variety of anti-CSF-1/CSF-1R therapies to either reduce or reprogram TAMs to treat cancer." (PMID 28629162, 2017). "However, our recent studies have shown that CSF-1R in cancer cells can be stimulated by colony stimulating factor secreted by tumor-associated macrophages." (PMID 23561040, 2013). "We also analyzed the CSF-1R-induced and CSF-1R-induced* proteins for significant association with disease and found a statistically significant enrichment for proteins involved in tumor metastasis and progression." (PMID 21049007, 2010). "In breast cancer, pancreatic cancer, and other solid tumors, high tumor CCL2 expression is associated with improved responsiveness to CCR2 or CSF1R inhibitors, indicating that CCL2 expression levels may serve as a predictive biomarker concerning the efficacy of TAM‐targeted therapy." (PMID 41426206, 2026). "In addition, these results partially agree with the observations obtained by genetic inactivation of Csf1r in Mir34a-deficient myeloid cells and further confirm Csf1r-inhibition as an important mediator of non-tumor-cell autonomous suppression of CACs by miR-34a." (PMID 39425000, 2025). "However, therapeutic approaches face contradictions; while TAM depletion (e.g., CSF-1R inhibitors) reduces tumor burden, it may impair anti-tumor immunity, whereas reprogramming strategies risk incomplete phenotype conversion or context-dependent efficacy." (PMID 40422244, 2025). "Therefore, blocking the CSF-1/CSF-1R axis could be effective for inhibiting the association between TAMs and tumor cells." (PMID 39169402, 2024).